NOX4 (NADPH oxidase 4)
Diseases named in the same sentence as NOX4 in open-access papers (continued):
Sharing a sentence is not in itself a finding about the gene and the disease.
diabetic nephropathy (continued). "In addition, Nox4 plays a key role in the pathogenesis of diabetic nephropathy by targeting renal fumarate hydratase, the enzyme that increases fumarate levels." (PMID 27649164, 2016). "These researchers demonstrated that miR-25 was a direct target of Nox4 3′-UTR and concluded that miR-25 may contribute to the regulation of Nox4 expression in diabetic nephropathy." (PMID 25298619, 2014). "Thus, it appears that Nox4 is a key upstream event in the pathogenesis of diabetic nephropathy with subsequent activation of PKC including PKC‐α leading to increased albuminuria as a result of increased VEGF and decreased nephrin expression." (PMID 25367693, 2014). "Since Nox4 is the major source of ROS in the kidneys during the early stages of diabetic nephropathy and in order to confirm the effect of TGFβ1 on ROS production, the levels of SOD1, which constitutes the first line of defence against ROS were determined following TGFβ1 treatment." (PMID 23991195, 2013). "In streptozotocin- (STZ-) induced diabetic nephropathy rats and high-glucose-induced podocytes, naringin attenuates renal function damage and inhibits podocyte apoptosis in diabetic nephropathy rats by inhibiting NADPH oxidase 4 and in vitro reactive oxygen species levels." (PMID 35465008, 2022). "In addition, Nox4 plays a critical role in mediating diabetic nephropathy and diabetic retinopathy." (PMID 25298619, 2014). "Similar studies have demonstrated that loganin and catalpol protect against podocyte death in diabetic nephropathy by inhibiting the AGEs/RAGE/p38MAPK/p65NF-κB and AGEs/RAGE/NOX4 pathways." (PMID 40429870, 2025). "Naringenin alleviates diabetic nephropathy and high-cholesterol diet-induced endothelial dysfunction by inhibiting NADPH oxidase 4 (NOX4) and NOX2." (PMID 36986070, 2023). "In the study of diabetic nephropathy, knockdown of NLRP3 decreased the expression of thioredoxin-interacting protein and NOX4 and the production of superoxide in the diabetic kidney, and improved renal function." (PMID 35711428, 2022). "NOX4, the major NADPH isoform in the kidney, contributes to redox processes involved in diabetic nephropathy, acute kidney injury, and other renal diseases by activating multiple signaling pathways." (PMID 35845925, 2022). "Moreover, Nox4 is the most abundantly expressed Nox isoform in the kidney, and it has been found to be upregulated and linked to the stimulation of TFG-β and matrix genes, leading to the activation of pro-fibrotic processes associated to kidney fibrosis in diabetic nephropathy." (PMID 34884897, 2021). "This study provides evidence that MYH9 downregulation in diabetic nephropathy induces podocyte dysfunction through the reorganization of the actin cytoskeleton, which is driven by TRPC6-mediated Ca2+ influx by NOX4-mediated ROS generation." (PMID 31118506, 2019). "NADPH oxidation is a major source of ROS production, and the NADPH oxidase 4 (NOX4) is the major active subgroup of NADPH oxidase, and high levels of ROS was important in the progression of diabetic nephropathy." (PMID 29383098, 2017). "Nox4 and uncoupled NOS are markedly upregulated in diabetic nephropathy, which together with impairment of mitochondrial metabolism are the main sources of ROS generation in the kidney and vascular tissues." (PMID 29333213, 2017). "We have also observed decreased HP DHA to VitC conversion in a model of diabetic nephropathy using db/db mice, and correlated this finding both to decreased GSH and increased NADPH oxidase 4 (Nox4) expression, reflecting increased superoxide generation." (PMID 28425467, 2017). "The importance of these findings is the link between Nox‐4 and PKC‐α activation leading to diabetic nephropathy." (PMID 25367693, 2014). "To investigate the role of oxidative stress and apoptosis, and the effects of dapagliflozin on the pathogenesis of diabetic nephropathy, we conducted DHE staining, Nox4 immunostaining and the TUNEL assay on the kidney." (PMID 24960177, 2014).
diabetic nephropathy (continued). "In diabetic nephropathy models, GKT137831 reduced glomerular ROS (measured by dihydroethidium staining), decreased albuminuria by over 50%, and attenuated mesangial expansion—effects that correlated with diminished NOX4 expression in podocytes." (PMID 40492113, 2025). "In a mouse model of streptozotocin‐induced diabetic nephropathy in ApoE−/− mice, the genetic deletion of NOX4 (but not NOX1), protected mice from structural and functional damage linked to diabetic nephropathy." (PMID 36658776, 2023). "In a diabetic kidney disease model, the lack of NOX4 and the expression of NOX5 enhanced albuminuria and renal fibrosis were enhanced, in part via TXNIP activation." (PMID 36358519, 2022). "However, unlike complications such as diabetic nephropathy, Nox4 has been shown to have a protective effect against atherosclerosis." (PMID 40864768, 2025). "Additionally, vitamin D supplementation in diabetic mice reduced oxidative stress-induced renal damage through upregulation of SIRT1 and subsequent reduction of NOX4, a NAPH oxidase, which is a characteristic isoform found in the kidney; a high level of NOX4 promotes diabetic nephropathy." (PMID 37047134, 2023). "Under the regulation of NOX4, TXNIP may inhibit the activation of NLRP3 inflammatory bodies by dissociating from Trx and binding with NLRP3, and PU may play a meaningful role in protection against diabetic nephropathy." (PMID 32456088, 2020).
atherosclerosis (86 papers, 2012 to 2025). A disease characterized by the build-up of fatty material and calcium deposition in the arterial wall resulting in partial or complete occlusion of the arterial lumen. "Numerous pathogeneses, such as cell senescence, apoptosis, endothelial dysfunction, angiogenesis, atherosclerosis and vascular ageing, cardiac remodeling, and neoplasms, have been linked to the NOX4 gene." (PMID 40711280, 2025). "Under hyperglycemic/diabetic conditions, NOX4 overexpression in endothelium is associated with atherosclerosis reduction in ApoE−/− mice." (PMID 38952543, 2024). "It was demonstrated that endothelial Nox4 protects against atherosclerosis, and the underlying mechanism involves the inhibition of soluble epoxide hydrolase 2 (sEH, gene EPHX2), a pro-inflammatory and atherogenic factor." (PMID 39598345, 2024). "In contrast, Nox4 deletion reduced lesion size and preserved plaque integrity, indicating a critical role for NOX4 in aging-associated atherosclerosis." (PMID 38975335, 2024). "To examine the impact of NOX4 on aging-associated atherosclerosis we initially determined atherosclerosis burden in four groups: young (5-month-old) and aged (16-month-old) Apoe-/- and Nox4-/-/Apoe-/- mice." (PMID 38975335, 2024). "In line, NOX1/NOX4 pharmacological inhibition and Nox1 deficiency significantly attenuate vascular ROS levels and atherosclerosis burden in ApoE−/− mice." (PMID 38952543, 2024). "While some studies suggest a vasculoprotective effect of Nox4, others have found that the global deletion of Nox4 is associated with increased atherosclerosis development in a diabetic atherosclerosis model." (PMID 38671903, 2024). "Increased expression and activity of NOX4 have been associated with mitochondrial oxidative stress, cardiovascular dysfunction, and atherosclerosis in aged mice." (PMID 37891912, 2023). "Age-associated increases in NOX4 expression and activity induces a proinflammatory phenotype in VSMCs that promotes atherosclerosis." (PMID 37891912, 2023). "Pharmacological inhibition of sEH by TPPU treatment firmly reduced ER stress and alleviated atherosclerosis caused by endothelial Nox4 dysfunction, which is considered as a major determinant of atherosclerosis under atherosclerosis-prone conditions." (PMID 35744996, 2022). "Previous studies have shown that NOX1 and NOX4, with proinflammatory actions, are implicated in the pathogenesis of cardiovascular disease and are highly associated with atherosclerosis." (PMID 32218307, 2020). "As the most widely distributed isoform of NADPH oxidase subunits, the Nox4 gene is reported to be associated with a variety of deleterious effects, including cell senescence and apoptosis, angiogenesis, vascular aging, atherosclerosis, and other malignancies." (PMID 31969899, 2019). "Although several researches showed that normal expression of Nox4 exerts protective effect on atherosclerosis, the increased level of Nox4 caused impaired ECs via inducing oxidative stress in HHcy." (PMID 30890956, 2019). "However, the age-associated increase in nuclear and mitochondrial 8-OHdG levels did not occur in aged Nox4-/-/Apoe-/- mice, supporting the notion that high NOX4 levels increase mitochondrial oxidative stress and cause DNA damage in aging atherosclerosis." (PMID 38975335, 2024). "The unique role of NOX4 in atherosclerosis may be linked to its production of H2O2, which functions as a second messenger widely involved in regulating cellular signaling pathways." (PMID 39867658, 2024). "We hypothesized that the NOX4-dependent mitochondrial oxidative stress promotes aging-associated atherosclerosis progression by causing metabolic dysfunction and inflammatory phenotype switch in macrophages." (PMID 38975335, 2024). "Thus, NOX4 protects against the development of endothelial dysfunction and atherosclerosis in conduit arteries in LDL-receptor-deficient mice." (PMID 38790608, 2024).
atherosclerosis (continued). "However, depletion of Nox4 caused increased atherosclerosis in the aortic sinus and common carotid artery." (PMID 37627585, 2023). "Moreover, increased Nox4 expression in aortic VSMCs of aged human subjects is associated with advanced atherosclerosis." (PMID 37891912, 2023). "However, in several other studies, NOX4 has been shown to have pathogenic roles in atherosclerosis, heart failure, and more recently in cognitive impairment and dementia." (PMID 35617030, 2022). "The uncontrolled production of ROS is directly linked to vascular damage and NOX proteins to ROS generation in the cardiovascular system: in mice, NOX1 and NOX4 isoforms are largely implicated in diabetic disease and atherosclerosis, and their deletion can significantly attenuate these pathologies." (PMID 32824091, 2020). "For this reason, the association of high levels of NOX2 and low levels of NOX4 may lead to the development of intimal hyperplasia, remodelling, and accelerated atherosclerosis in vein grafts." (PMID 29430280, 2017). "Nox4 deficiency results in resistance to flagellin-induced atherosclerosis in ApoE KO mice." (PMID 28018358, 2016). "However, in models for experimental atherosclerosis research such as genetically susceptible mice and primate, Nox4 protein content in aortic vessels has been found to remain stable." (PMID 25866599, 2015). "In conclusion, our data suggest that monocytic Nox4 is a central regulator of actin dynamics, and induction of Nox4 is the rate-limiting step in metabolic stress-induced monocyte priming and dysfunction associated with accelerated atherosclerosis and the progression of atherosclerotic plaques." (PMID 23825596, 2013). "In summary, our study provides new insights into the role of Nox4 in monocyte adhesion and migration and new molecular details of the mechanisms involved in monocyte dysfunction associated with metabolic disorders and chronic inflammatory diseases, including atherosclerosis." (PMID 23825596, 2013). "In aging, increased expression of NOX4 encoding for NADPH oxidase 4 induces mitochondrial dysfunction and a pro-inflammatory phenotype, advancing atherosclerosis." (PMID 40725452, 2025). "On the other hand, there are some reports that indicate the involvement of NOX4 in the development of atherosclerosis." (PMID 40227238, 2025). "Hyperhomocysteinemia plays a vital role in the development of atherosclerosis and has been associated with the activation of the PERK/p-eIF2α/CHOP signaling pathway, increased NOX4 expression, and increased cell apoptosis." (PMID 41511286, 2025). "It is also suggested that the increased activity of NOX4 observed in the course of atherosclerosis increases the production of ROS in mitochondria." (PMID 40227238, 2025). "The current study has shown that silencing NOX4 in hepatocytes reduces insulin and fatty acid utilization, but its metabolic role in atherosclerosis remains to be elucidated." (PMID 39867658, 2024). "Unlike the harmful effects of other NOX isoforms, the roles of NOX4 in atherosclerosis remain under discussion." (PMID 39867658, 2024). "On the other hand, young hypercholesterolemic mice with Nox4 deletion exhibited an increase in atherosclerosis, while endothelial-specific NOX4 overexpression protected against atherosclerosis." (PMID 38975335, 2024). "To investigate the effects of NOX4 inhibitor on macrophage mitochondrial function and metabolic phenotype in atherosclerosis, we first measured the levels of mitochondrial ROS in macrophages derived from aged Apoe-/- mice." (PMID 38975335, 2024). "A recent study also reported that TLR5-NADPH oxidase 4 (Nox4) promotes the migration of smooth muscle cells in atherosclerosis and facilitate the formation of atherosclerotic plaque." (PMID 39021802, 2024). "Analysis of these keywords indicates that this cluster focuses on the role of oxidoreductases (such as NOX2 and NOX4) and apolipoproteins in atherosclerosis." (PMID 39610974, 2024).
atherosclerosis (continued). "Additional studies have consistently shown that genetic deletion of NOX4 increases atherosclerosis in ApoE−/− mice." (PMID 38952543, 2024). "Our findings suggest that increased NOX4 in aging drives macrophage mitochondrial dysfunction, glycolytic metabolic switch, and pro-inflammatory phenotype, advancing atherosclerosis." (PMID 38975335, 2024). "Previous studies showed that inhibition of NOX4 or mitochondrial ROS in VSMC during aging atherosclerosis reduces vascular inflammation." (PMID 38975335, 2024). "Whereas some studies support the concept that NOX4 is a mediator of atherosclerosis during hypercholesterolemia, other groups have reported opposing findings." (PMID 37873768, 2023). "In the vasculature, NOX4 protects against endothelial dysfunction, leucocyte adhesion, inflammation, and atherosclerosis." (PMID 33881501, 2022). "NOX4 expression in coronary artery intima increases with atherosclerosis severity in transplanted hearts." (PMID 35883899, 2022). "The safety and efficacy of long-term Nox4 inhibition need to be carefully evaluated and take into consideration the protective effects of Nox4 in atherosclerosis and vascular remodeling." (PMID 35617030, 2022). "We, then examined the expression of mIR-25 in SVECs from patients with advanced atherosclerosis and type 2 diabetes, showing increased mIR-25 consistent with the reduced Nox4 seen in ECs from these patients." (PMID 34420367, 2021). "To take this a step further, we expressed mutant IGF-1R in SVECs from patients with advanced atherosclerosis and demonstrated a reduction in mIR-25 expression and an increase in Nox4 expression." (PMID 34420367, 2021). "In this regard, the overexpression of NOX4 in artery wall of aged subjects aggravates atherosclerosis." (PMID 32664383, 2020). "Among the NADPH oxidases, NOX4 is currently the most studied in relation to atherosclerosis, as it is believed to have atheroprotective properties." (PMID 32664404, 2020). "Human studies reported the effects of NOX4 on vascular tissues such as coronary and peripheral arteries with contribution to atherosclerosis and endothelial dysfunction in these vessels." (PMID 32298299, 2020). "Atherosclerosis development involves multiple cell types, which all express NOX4 at basal levels and as such it is expected that NOX4 plays a role; albeit several studies have suggested both an athero-protective and a deleterious role." (PMID 32923955, 2019). "Here, we demonstrate that TLR5-mediated Nox4 activation regulates the migration of SMCs, leading to neointimal plaque formation in atherosclerosis." (PMID 31292433, 2019). "Endothelial NOX4 plays a critical role in the control of atherosclerosis where ROS is athero-protective via NOX4-dependent inhibition of inflammation and vascular remodeling." (PMID 31428618, 2019). "Taken together, these results demonstrate that TLR5-mediated Nox4 activation regulates the migration of SMCs, leading to neointimal plaque formation in atherosclerosis." (PMID 31292433, 2019). "Reports in the literature support the idea that Nox4 is protective, while Nox1 is deleterious for atherosclerosis development." (PMID 29710840, 2018). "This review focuses on the role of the mitochondria and the nicotinamide adenine dinucleotide phosphate (NADPH) oxidases Nox1 and Nox4 in vascular senescence, and their contribution to the development of atherosclerosis." (PMID 29710840, 2018). "In ApoE−/− mice, overexpression of Nox4 in endothelial cells reduced atherosclerosis, mainly in the abdominal section of the descending aorta, in animals fed a Western diet for 24 weeks." (PMID 29710840, 2018).